TLR4 (toll like receptor 4)
Diseases named in the same sentence as TLR4 in open-access papers (continued):
Sharing a sentence is not in itself a finding about the gene and the disease.
gout (48 papers, 2013 to 2026). A condition characterized by painful swelling of the joints, which is caused by deposition of urate crystals. "The aim of the present study was to investigate the link among TLR4 gene polymorphisms at various loci, protein expression, and gouty arthritis susceptibility." (PMID 38652726, 2024). "Studies have shown that gout caused by urate was mediated by the TLR4/NF-κB signaling pathway, and the IL-1β released was linearly related to it." (PMID 34552978, 2021). "In this regard, a previous work reported that the risk of gout—a pathology known by deposition of monosodium urate crystals in joints—is directly associated with the polymorphism rs2149356 related to high TLR4 production." (PMID 32283759, 2020). "In contrast, genetic variance in TLR4 has been linked with gout risk in some populations, but with widely differing results, and the impact is less clear for the heritable variance of TLR4 in gout." (PMID 28818081, 2017). "Here we attempted to replicate the previously reported association with gout of TLR4 variant rs2149356 in Han Chinese in sample sets of European and Polynesian ancestry." (PMID 26808548, 2016). "Conversely the TT-genotype associated with reduced levels of TLR4 mRNA in PBMCs from people with intercritical gout." (PMID 26808548, 2016). "The T-allele of single nucleotide polymorphism rs2149356 in TLR4 is a risk factor associated with gout in a Chinese study." (PMID 26808548, 2016). "On balance we are unable to conclude that the TLR4 locus to be the first replicated genetic risk factor in gout outside of those that influence gout risk via modulation of serum urate levels." (PMID 26808548, 2016). "Understanding how the T-allele controls expression of TLR4 will be important for improved molecular understanding of the pathogenic role of the TLR4-pathway in gout." (PMID 26808548, 2016). "In conclusion, TLR4 SNP rs2143956 is associated with gout risk in prevalent clinically-ascertained gout in Europeans, in a direction consistent with previously published results in Han Chinese." (PMID 26808548, 2016). "In conclusion TLR4 SNP rs2143956 associates with gout risk in prevalent clinically-ascertained gout in Europeans, in a direction consistent with previously published results in Han Chinese." (PMID 26808548, 2016). "Additionally, we have conducted preliminary elucidations of its anti-gout properties, which are associated with the modulation of the TLR4/NF-κB signaling pathway." (PMID 40365321, 2025). "The AG genotype of the TLR4 gene rs2737191 polymorphism may be correlated with the development of gouty arthritis." (PMID 38652726, 2024). "rs2149356 is the only variant currently associated with increased risk of gout in Han Chinese and European populations and may play a regulatory role of TLR4 expression and IL-1 serum levels during flares." (PMID 33926105, 2021). "A TLR4 single nucleotide polymorphism (SNP; rs2149356) has been reported to be associated with gout in a Han Chinese sample set, where the TT-genotype was associated with an increased risk of gout (OR = 1.96 [95% CI 1.40–2.74])." (PMID 26808548, 2016). "However, given the very strong prior functional candidacy of TLR4, we do consider that our study provides evidence consistent with a causal role for TLR4 in gout." (PMID 26808548, 2016). "However, there is only one replicated association of an immune gene with gout: an SNP within the candidate TLR4 innate immune gene is associated with gout in Chinese (OR = 1.42, P < 1 × 10−4)." (PMID 25889045, 2015). "The T allele of CARD8 rs2043211 (C10X) has been associated with increased risk of gout in Chinese, and rs2149356 in toll-like receptor 4 (TLR4), a receptor functionally implicated in MSU-stimulated inflammation, has also been associated with serum IL-1β levels and the risk of gout in Han Chinese." (PMID 26462562, 2015).
gout (continued). "The aim of this present study was to determine whether the TLR4 gene rs2149356 SNP is associated with gouty arthritis (GA) susceptibility and whether rs2149356 SNP impacts the TLR4-IL1β signaling pathway molecules expression." (PMID 23738004, 2013). "The Polynesian population could be important in trans-ancestral genetic fine-mapping of the etiological variant in TLR4 with the variant expected to be in a genomic segment with the same alleles associated with gout between Han Chinese, European and Polynesian." (PMID 26808548, 2016). "In conclusion, our findings indicate that the TLR4 gene rs2149356 SNP is associated with gout susceptibility, and might be involved in regulation of innate and adaptive immunity in gouty inflammation, that is might be participated in the regulating serum lipid metabolism in GA patients." (PMID 23738004, 2013). "The TLR4/NF-κB signaling pathway serves as the critical “priming signal” for inflammasome activation in gout pathogenesis." (PMID 41583434, 2025). "Serum samples were collected from 41 gouty arthritis patients (gout group) and 82 healthy individuals (control group), and TLR4 protein concentrations were determined." (PMID 38652726, 2024). "The level of TLR4 protein expression is significantly higher in patients with gouty arthritis than in controls, and there is a correlation between high TLR4 protein expression and the development of gouty arthritis." (PMID 38652726, 2024). "Although the important role of the TLR4-NF-κB signaling pathway in the pathogenesis of gouty arthritis has been demonstrated, few drugs have been studied to target this pathway for the treatment of gouty arthritis." (PMID 38652726, 2024). "In animal experiments, researchers confirmed the role of the TLR4 gene in the urate-mediated inflammatory cascade response in gout." (PMID 38652726, 2024). "The TLR4 protein level in the gout group (19.19±3.09 ng/ml) was significantly higher than that in the control group (15.85±4.75 ng/ml)." (PMID 38652726, 2024). "Traditional Chinese Medicine studies have shown that TLR4 is overexpressed in a gout mouse model and that anti-inflammatory treatment reduces TLR4 protein expression." (PMID 38652726, 2024). "The expression of the inflammasome (TLR4 and NLRP3) is associated with acute gout inflammation, which was determined by western blot, and WPP and CPP inhibited the expression of TLT4 and NLRP3." (PMID 36339594, 2022). "Extracellular UA and MSU have been recognized by TLR2 and TLR4 in gouty arthritis and activate the MAPK, NLRP3 and NF-κB signaling pathways, thus initiating the inflammatory response." (PMID 36438835, 2022). "In conclusion, ELB is protective in rats with chronic alcoholic liver injury and gouty arthritis, possibly mediated by the inhibition of TLR4/MyD88/NF-κB, NLRP3, and JAK2-STAT3 signaling pathways in both the hepatic and synovial tissues." (PMID 36176434, 2022). "IL-1β is an important inflammatory mediator of gouty arthritis, which is mainly produced through the TLR4-NF-κB and NLRP3 inflammasome signaling pathways." (PMID 33935726, 2021). "The results of cell experiments were highly consistent with the results of the animal experiments, further suggesting that the active flavonoids can attenuate gouty arthritis by regulating the TLR4/MyD88/NF-κB pathway and NLRP3 levels." (PMID 34803702, 2021). "The pathogenic role of TLR-4 and the potential therapeutic effect of CUR have been evaluated also in gout, a common inflammatory arthritis due to the deposition of monosodium urate (MSU) crystals in articular and periarticular tissues." (PMID 32225104, 2020). "As illustrated in some research studies, NOD-like receptor protein-3 inflammasome (NLRP3) and toll-like receptor-4 (TLR4) plays an important role during gouty arthritis." (PMID 32082152, 2019). "A previous study demonstrated that TLR4 mediated the initial steps of gout pathogenesis and that TLR4 expression was pivotal to MSU crystal-induced inflammation." (PMID 31455356, 2019).
gout (continued). "A small but significant increase in the risk of gout has been linked with functional variants in the inflammasome component caspase activation and recruitment domain (CARD) gene CARD8, IL1B, and the TLR4 and TLR2 receptor complex co-receptor molecule CD14." (PMID 28818081, 2017). "Previous studies have identified polymorphisms in the NALP3 inflammasome, TLR-4, CARD8, IL-1β, IL-18, and CD14 genes to be associated with gout." (PMID 29023487, 2017). "Together, these findings suggest that TLR2 and TLR4 are key drivers of IL-1 family cytokine signaling in gout and may play a central role in disease exacerbation." (PMID 40709261, 2025). "Targeting IL1A, either alone or in combination with TLR4 suppression, may be a promising treatment strategy for gout-related inflammation and tissue damage." (PMID 40657393, 2025). "Relevant studies have shown that activation of TLR4 can activate the MAPKs signaling pathway, thereby regulating the release and expression of inflammatory cytokines, exacerbating the disease progression of gout and its complications." (PMID 39534253, 2024). "Moreover, TLR4 protein is highly expressed in the gout population, and it increases with increasing UA levels in this population." (PMID 38652726, 2024). "In the current study, the decrease in the incidence of gout resulting from long-term statin use might also involve the inhibition of TLR4/MyD88/NF-κB signaling." (PMID 36873987, 2023). "Therefore, in the present study, the underlying protective role and mechanism of ELB involved in TLR4/NF-κB, NLRP3, and JAK2/STAT3 inflammatory signaling pathways were investigated in chronic alcoholic liver injury combined with gouty arthritis." (PMID 36176434, 2022). "In conclusion, we hypothesize that P. igniarius may down-regulate MSU crystal-induced gout-related inflammatory factor expression in HUVECs through mediating the TLR4/NF-κB/NLRP3 signaling pathway." (PMID 36339594, 2022). "In conclusion, the current study indicates that ELB exhibits a protective effect in rats with chronic alcoholic liver injury and gouty arthritis, possibly mediated by inhibiting TLR4/MyD88/NF-κB, NLRP3, and JAK2-STAT3 signaling pathways in both the hepatic and synovial tissues." (PMID 36176434, 2022). "In conclusion, the present study demonstrated that three active flavonoids (luteolin, luteoloside, and apigenin) from Lagotis brachystachya attenuate MSU crystal-induced gouty arthritis via inhibiting TLR4/MyD88/NF-κB and NLRP3 expression in the aspect of animal experiment and cell experiment." (PMID 34803702, 2021). "At the onset of gouty arthritis, TLR4 signaling pathway was involved in regulating cell pyroptosis." (PMID 33430857, 2021). "The most important of these receptors is TLR4, which is particularly involved in gout inflammation." (PMID 33488933, 2020). "In gouty arthritis, Lian and colleagues elucidated that circHIPK3 was enriched in mononuclear cells of synovial fluid, which strikingly repressed miR-561 and miR-192, and thereby facilitated pro-inflammatory functions of toll-like receptor 4 (TLR4) and NLR family pyrin domain containing 3 (NLRP3)." (PMID 36292157, 2022). "Thus, there is a need for a gout GWAS in clinically ascertained sample sets in order to identify non-serum urate genetic risk factors for gout (for example, TLR4) which are likely to have weak effects (OR <1.4)." (PMID 25889045, 2015). "Additionally, we intended to determine whether the rs2149356 SNP impacts the expression of TLR4-IL11β signaling pathway molecules in peripheral blood from patients with gout." (PMID 23738004, 2013). "Therefore, we speculate that the mechanism of resveratrol in anti-gouty arthritis may involve inhibiting the NLRP3-mediated TLR4/MyD88/NF-κB pathway by regulating relevant metabolic pathways, thereby inhibiting pyroptosis and slowing down the inflammatory response." (PMID 39534253, 2024).
gout (continued). "The target genes of Terpine-4-ol, a main compound of ZP, were overlapped with the gouty arthritis-related genes such as NLRP3, PTGS2, CXCL8, IL6, TNF, IL1B, TLR4, and ALB." (PMID 39861092, 2024). "As we observed the important role of HSP60 in the TLR4 signaling pathway and NLRP3 inflammasome activity, this prompted us to investigate its role in gout." (PMID 33488933, 2020). "The inhibitory effect of TLR2 and TLR4 neutralizing antibodies supports a role for TLR2 and TLR4 in mediating the initial steps of gout pathogenesis." (PMID 30157934, 2018). "The potential pivotal role of the components of innate immunity, especially TLR2/TLR4 and the NLRP3 inflammasome, in this disease, seems attractive as potential target candidates for the treatment of gout." (PMID 23738004, 2013). "In gouty arthritis, MSU crystal stimulation could prime macrophages triggering Toll-like receptor (TLR) 2 or TLR4 as the signal 1 and activating the NF-κB." (PMID 36248423, 2022). "In the stage of acute gouty arthritis, the MSU crystal activates TLRs such as TLR2 and TLR4." (PMID 34803702, 2021). "In the present study, the effects of the active flavonoids were evaluated in rats or Raw264.7 cells with gouty arthritis induced by monosodium urate (MSU) crystal, followed by the detection of TLR4, MyD88, pNF-κB, and NLR family pyrin domain-containing 3 (NLRP3) expression." (PMID 34803702, 2021). "Since uric acid was first considered a signal sensed by innate immunity (including TLR4 activation and NLRP3 inflammasome in gouty arthritis), the role of uric acid metabolism in immune activation and inflammation has become the current direction and hotspot concerning gout." (PMID 29415757, 2018).
non-alcoholic fatty liver disease (44 papers, 2011 to 2025). "Luteolin is associated with the progression of nonalcoholic fatty liver disease by suppressing the TLR4/NF-κB pathway to change gut bacterial species." (PMID 38997762, 2024). "In alcohol-induced liver injury, the activation of Kupffer cells depends on TLR4, and in non-alcoholic fatty liver disease TLR4 deficiency reduces hepatic lipid accumulation and inflammation after a methionine-choline-deficient diet." (PMID 27391331, 2016). "It appears that TLR-2 deficiency protects from nonalcoholic fatty liver disease and probably modifies the signaling pathway of TLR-4." (PMID 22114589, 2011). "TLR4 and 9 have been reported as the critical factors in the progression of non-alcoholic fatty liver disease (NAFLD) and involve in mediating neutrophil dysfunction in cases of alcoholic hepatitis." (PMID 37822929, 2023). "Toll-like receptor 4 and proinflammatory cytokines play a central role in the progression of nonalcoholic fatty liver disease." (PMID 26629827, 2015). "TLR-2 deficiency appears to play a protective role in induction of nonalcoholic fatty liver disease and probably modify TLR-4 signaling." (PMID 22114589, 2011). "Concurrently, animals lacking TLR4 exhibit a reduced susceptibility to non-alcoholic fatty liver disease (NAFLD)." (PMID 38891768, 2024). "Betaine can also inhibit high-mobility group box protein 1/TLR4 signal transduction, which may be one of the mechanisms of betaine in the treatment of liver injury in rats with non-alcoholic fatty liver disease." (PMID 35892549, 2022). "Similarly, LBP (glucan type) remarkably downregulated the level of Proteobacteria, and reduced the LPS/TLR4/NF-κB signaling path in high-fat diet (HFD)-induced nonalcoholic fatty liver disease (NAFLD) in Sprague–Dawley (SD) rats." (PMID 37430929, 2022). "Importantly, several lines of evidence have described the involvement of the LPS/TLR-4 pathway in non-alcoholic fatty liver disease (NAFLD) pathogenesis and in its progression to the more severe form of non-alcoholic steatohepatitis (NASH)." (PMID 26573228, 2015). "For example, the treatment study of Erchen decoction in nonalcoholic fatty liver disease (NAFLD) has shown that the interactions of active ingredients of Erchen decoction with 77 targets related to NAFLD mainly reduces inflammation’s stimulation of the liver through the TLR4 signaling pathway." (PMID 36313288, 2022). "We found that TLR4/MyD88 signaling in liver parenchymal cells plays a pivotal role during the early progression of HFD-induced nonalcoholic fatty liver disease (NAFLD), in which free HMGB1 served as a positive component mediating TLR4 activation." (PMID 34916485, 2021). "Additionally, vitamin B6 has been found to improve non-alcoholic fatty liver disease in mice through the PPAR and TLR4/NF-κB signaling pathways." (PMID 40078416, 2025). "Research elucidates a novel HMGB1-mediated inflammatory pathway in Non-Alcoholic Fatty Liver Disease (NAFLD), revealing a redox signaling mechanism where ONOO-, formed through NADPH oxidase activation, plays a pivotal role in TLR-4 activation and cytokine release." (PMID 39076514, 2024). "In HBV-transgenic mice, saturated fatty acids (SFAs), potential ligands for TLR4, were shown to accelerate TLR4 signaling, which inhibited HBV replication in CHB infection with non-alcoholic fatty liver disease, suggesting an antiviral role of TLR4 against HBV infection." (PMID 34638802, 2021). "Similarly, increases in hepatic tenascin-C expression occur in obese individuals with non-alcoholic fatty liver disease (NAFLD), and in each of these scenarios tenascin-C interacts with TLR4 to augment local tissue inflammation." (PMID 29137117, 2017).
non-alcoholic fatty liver disease (continued). "For instance, in a non-alcoholic fatty liver disease (NAFLD) model study, it was found that Lcn-2 could trigger the secretion of HMGB1, activate TLR4 signaling pathway, induce NOX-2 expression, increase ROS production, then cause neuronal oxidative damage, which increase neuroinflammation." (PMID 38533497, 2024). "Moreover, anti-inflammation, antioxidation, and immune regulation with the regulation of TLR4-NF-κB, ROCK/NF-κB, HO-1, mitochondria-dependent as well as HMGB1‐TLR4 signaling pathways are correlated with hepatic protection in liver injury and nonalcoholic fatty liver disease." (PMID 32410996, 2020). "There were studies which showed that the intestinal injury in diet-induced nonalcoholic fatty liver disease models could be improved after green tea extract (GTE) treatment which correlated with bile metabolism through lowering TNF-R1, TLR4, and NF-κB expression." (PMID 31933540, 2019). "Therefore, endocytosis of TLR4 and NOX2 into macrophages might be a novel therapeutic target for non-alcoholic fatty liver disease." (PMID 29269727, 2017).